INS (insulin)
Diseases named in the same sentence as INS in open-access papers (continued):
Sharing a sentence is not in itself a finding about the gene and the disease.
diabetes (continued). "About two-thirds (66%) met the criteria for pre-diabetes; the remainder had diabetes not prescribed insulin." (PMID 41254652, 2025). "One study reported that FGF21, along with GLP‐1, contributes to the prevention of insulin‐induced diabetes in mice without glucagon action." (PMID 40919135, 2025). "Among the 14 incorrect answers, 48% (n=24) of respondents selected “patients with diabetes using insulin” rather than the correct indication (“patients with HbA1C count ≥6.6%”), which was only selected by 38% (n=19) of the respondents." (PMID 40777676, 2025). "By 2016, about 60% of patients with diabetes requiring insulin therapy in Syria lacked access to the insulin." (PMID 41343509, 2025). "Diabetes mellitus (DM), a human disease characterized by sustained high blood glucose levels, is caused by the β-cells of the pancreas not producing sufficient insulin (type 1; T1DM) or by the cells of the human body developing resistance to insulin (type 2; T2DM)." (PMID 39796218, 2025). "The cost of devices and diabetes supplies are among the most common barriers to diabetes technology use, and these barriers are exacerbated for PWD with high TDI requirements who require more insulin and pump supplies." (PMID 41230085, 2025). "Diabetes is a chronic metabolic disorder with high blood sugar levels due to a lack of insulin or a lack of effective utilization of insulin, which is a hormone that regulates glucose levels." (PMID 41266649, 2025). "Regardless of the type of insulin delivery system, nutritional choices play a crucial role in diabetes management." (PMID 41156556, 2025). "Priming the insulin pen was significantly influenced by duration of diabetes (p < 0.001), insulin therapy duration (p < 0.001), and age (p = 0.028), but not by the device type (p = 0.054)." (PMID 41306599, 2025). "Taken together, these results undermine the central premise of the carbohydrate-insulin model and do not support its application as an explanatory framework for glucose dysregulation or diabetes pathophysiology." (PMID 40837433, 2025). "It should be noted that in the current study population with a mean diabetes duration of 26 years there probably is no residual c-peptide production, i.e., no endogenous insulin secretion, as there is complete destruction of beta cells." (PMID 40002779, 2025). "She tested positive for the diabetes autoantibodies GAD 65, ICA 512, and insulin autoantibody." (PMID 40612706, 2025). "Interestingly, in endothelial cells derived from individuals with diabetes, liraglutide alleviated endoplasmic reticulum stress, reduced c-Jun N-terminal kinase (JNK) activity, and restored insulin-mediated eNOS activation." (PMID 41008590, 2025). "Diabetes Mellitus (DM) is a chronic disease in which the body does not produce insulin or cannot properly use the insulin it produces." (PMID 41370536, 2025). "While we usually rely on fasting plasma glucose and insulin concentrations to confirm compliance in studies excluding individuals with diabetes, this approach is not feasible when including people with diabetes." (PMID 40474966, 2025). "Such advancements could help reduce the burden to HCPs and improve the care for people living with diabetes by reducing the amount of CBG testing and optimising insulin dosing." (PMID 41354385, 2025). "SHP2 deregulation was shown to be involved in insulin resistance in type 2 diabetes mellitus (T2DM); accordingly, SHP2 inhibition or liver-specific PTPN11 deletion delayed IR endocytosis, enhanced insulin-activated AKT pathway and improved insulin sensitivity in mice." (PMID 41302504, 2025). "Type 2 diabetes mellitus (T2DM) is a common metabolic condition characterized by a combination of two factors: impaired insulin production by pancreatic β-cells and failure of insulin-sensitive tissues to respond." (PMID 39917540, 2025).
diabetes (continued). "Diabetes mellitus (DM) is one of the most common metabolic conditions, either a lack of insulin production or the body's inability to respond to insulin." (PMID 40994873, 2025). "In addition to insulin and mitochondrial-targeted therapies, metabolic modulators like sodium-glucose cotransporter 2 (SGLT2) inhibitors, commonly used to treat diabetes, are being investigated for their potential to enhance wound healing." (PMID 40280905, 2025). "Among the group with diabetes, 25% were diet-controlled, 54% were treated with noninsulin medications (usually metformin), and 21% were undergoing insulin therapy." (PMID 40759177, 2025). "Our study found patients who did not use insulin for the treatment of their diabetes had more occurrences of fractures than those who used insulin." (PMID 40308354, 2025). "Third, patients with diabetes mellitus were not excluded and postoperative insulin use not considered." (PMID 40260105, 2025). "Research indicates that both exercise and metformin enhance insulin sensitivity by activating the AMPK signaling pathway in skeletal muscle, making them effective strategies for preventing the progression from prediabetes to diabetes." (PMID 41357171, 2025). "It offers improved metabolic control, eliminating the need for exogenous insulin therapy and may provide additional organ support when combined with kidney transplantation (SKP) in patients with diabetes and ESKD." (PMID 40071060, 2025). "There was no history of diabetes mellitus, prolonged fasting, alcohol excess, or access to exogenous insulin or oral hypoglycemic agents." (PMID 40270996, 2025). "In participants without diabetes, lower serum calcium levels were significantly correlated with lower insulin, HbA1c, TC, HDL‐C, LDL‐C, TG, uric acid, urine albumin‐to‐creatinine ratios, and higher eGFRs (all p < 0.05)." (PMID 41000256, 2025). "Moreover, we indicate the impact of oxidative stress in diabetes, noting how TIM is affected by reactive oxygen species, which can disrupt normal cellular functions and insulin signaling." (PMID 41009376, 2025). "T2DM (Type 2 diabetes mellitus) is a long-term metabolic condition primarily defined by high blood glucose levels due to insulin resistance and/or a relative lack of insulin." (PMID 40655404, 2025). "Also, he had diabetes, undergoing treatment with Neutral Protamine Hagedorn (NPH) insulin, and ischemic heart disease." (PMID 40453447, 2025). "Type 1 diabetes mellitus (T1DM), previously known as juvenile or insulin-dependent diabetes, is a chronic autoimmune disease resulting from the destruction of pancreatic β-cells, leading to insufficient insulin and hyperglycemia." (PMID 41162165, 2025). "As γδ T cells recognize certain insulin antigens and their TCR activation involves MAPK pathways, investigating whether insulin promotes γδ T cell function to aid wound healing in diabetes presents a promising avenue for future research." (PMID 41341586, 2025). "Exercise and intermittent fasting have long been recognized as essential non-pharmacological treatments for diabetes because they can improve insulin sensitivity and insulin-stimulated muscle glucose uptake, both of which improve glucose utilization." (PMID 41394924, 2025). "There were six patients with the INS variant, four with the ABCC8 variant and one with the HNF1B variant without a family history of diabetes." (PMID 40303944, 2025). "Long-term mortality was higher in diabetes vs. non-diabetes, and especially in insulin- vs. non-insulin-treated diabetes regardless of undergoing PCI or CABG." (PMID 40810069, 2025). "For instance, it is a wise strategy to not take insulin at dinner if they know they will be consuming alcohol, even though that advice contradicts regular guidelines for diabetes management." (PMID 39997249, 2025).
diabetes (continued). "For those with “un-classified” diabetes at onset (N = 35), 11 persons were ultimately diagnosed with T1DM, with the majority of them receiving basal-bolus insulin treatment and only one person receiving a combination of basal-bolus insulin and OHAs." (PMID 41225468, 2025). "Post-mortem pancreatic sections from 24 people with CF and 10 organ donors without CF or diabetes were stained for insulin/glucagon/vimentin and Sirius red/fast green with collagen distribution assessed semi-quantitatively and quantitatively (non-CF)." (PMID 39836539, 2025). "The number of ALDH1A3-positive (a biomarker of β-cell dedifferentiation), insulin-negative cells was threefold higher in individuals with diabetes." (PMID 41473243, 2025). "Treatment options for diabetes vary depending on the combination of CGM and insulin administration method (such as multiple daily injections [MDI] or continuous subcutaneous insulin infusion [CSII]), and it is important to consider the best treatment for each individual." (PMID 39052201, 2025). "No diabetes mellitus factors measured were significantly associated with an increased or decreased risk of developing wet AMD such as glucose, insulin and C-Peptide." (PMID 39930367, 2025). "Experimental and clinical evidence suggests that, during the early stages of the onset of type 2 diabetes mellitus (T2DM), the β-cell works diligently to increase the biosynthesis and release of insulin to compensate for insulin resistance in the target peripheral tissues." (PMID 40710299, 2025). "The absence of diabetes likely indicates a lower baseline level of IR, which enhances the beneficial effects of improved insulin sensitivity on liver health." (PMID 40520791, 2025). "Preterm delivery (< 37 weeks) was more common with insulin pumps (25.9% vs. 16.7%, P = 0.01), as was caesarean section (59% vs. 40%, P = 0.04), which was independent of diabetes duration, age and microvascular complications." (PMID 40759795, 2025). "Pharmacists can inform patients that diabetes occurs when sugars are not properly stored in the blood, preventing the normal regulation of the body’s natural insulin." (PMID 40507585, 2025). "Diabetes mellitus is a chronic condition where the body does not produce enough or effectively use insulin, leading to high blood glucose levels." (PMID 40737300, 2025). "Insulin and SGLT2i represent the most efficacious and safest options among antidiabetic treatments for PTDM, supporting their preferential consideration in post-transplant diabetes management." (PMID 40995094, 2025). "In this article, we present the case of a cirrhotic patient, initially not known to have diabetes or prediabetes, who developed fulminant diabetes overnight, with massive resistance to subcutaneous insulin treatment." (PMID 40491591, 2025). "Patients aged 18 to 77 years with prediabetes or diabetes not using insulin and reporting low physical activity were potentially eligible." (PMID 41254652, 2025). "Modern diabetes technologies like personal insulin pumps and continuous glucose monitoring can help to minimize the deteriorating effect of JIA exacerbations and rheumatoid treatment on metabolic control of diabetes." (PMID 40510579, 2025). "This unique secretome of VAT has a distinct and negative impact on hepatocyte and muscle insulin action, highlighting the depot-specific differences in adipose tissue secretome composition and their effects on metabolic syndrome and diabetes." (PMID 40248509, 2025). "We confirm that abundant small, insulin-positive EOs are present in donors without diabetes and comprise most of the pancreatic endocrine area in early life." (PMID 41223263, 2025). "Ten semi‐structured phone interviews were held with older adults with diabetes, with or without frailty, treated with insulin while undergoing surgical hospital admission." (PMID 41358572, 2025).
diabetes (continued). "Polygenic risk score analysis for traits relevant to diabetes found that C-reactive protein showed a positive association, whereas PRS for fasting insulin showed a negative association with neuropathic pain, in individuals with diabetic polyneuropathy." (PMID 39471050, 2025). "In the early stages of diabetes, the lack of insulin or insulin resistance induces cardiomyocytes to increase fatty acid uptake and β-oxidation to sustain ATP production." (PMID 40598681, 2025). "After a number of years, some of the volunteers developed diabetes and Dr. Clifton Bogardus, III who served as chief of the Clinical Diabetes and Nutrition section of NIDDK from 1985 to 2000, and his team were able to determine that insulin resistance and obesity were major predictors of disease." (PMID 40405667, 2025). "Additionally, Rk1 reduces pancreatic weight and increases pancreatic insulin levels, thereby protecting the pancreas from high-fat diet (HFD)-induced diabetes." (PMID 40432897, 2025). "Insulin therapy, which is often indicative of advanced diabetes or severe β-cell failure, similarly showed no sex difference or significant association with the prevalence of DSPN in the current cohort." (PMID 40869604, 2025). "Severe hypoglycemia is frequently encountered in patients with diabetes treated with insulin or insulin secretagogues, but in patients without diabetes, hypoglycemia is unusual, and the symptomatology is often misinterpreted." (PMID 39941267, 2025). "The effect of exercise training on improving the impaired insulin signaling pathway is limited, but the noninsulin signaling pathway of these diabetes patients is intact." (PMID 40362436, 2025). "We interpret this as indicating that decreased insulin sensitivity alone does not lead to diabetes unless the beta-cell function is also impaired." (PMID 40568093, 2025). "Type 2 Diabetes Mellitus (T2DM) is a metabolic disease characterized by insulin resistance and high plasma glucose levels, which occur when the skeletal muscle, liver and adipose tissue cells fail to respond properly to insulin." (PMID 40142334, 2025). "In our experiment, the lowering of glucose level and increase in insulin level in the diabetes + naringin group were not statistically significant." (PMID 40161891, 2025). "While the fasting insulin concentrations were elevated in the diabetes group (145.8 vs. 86.4 pmol/L), this difference was not statistically significant (p = 0.13)." (PMID 40217596, 2025). "The first relates to the preservation or lesser impairment of pancreatic beta cells, characterized by higher C-peptide levels, shorter diabetes duration, younger age, and adequate glycemic control without the need for insulin." (PMID 41417301, 2025). "Our classification of diabetes type was on clinical grounds, as we did not do auto-antibodies such as anti-glutamic acid decarboxylase antibody and anti-insulin antibody to diagnose type 1 DM." (PMID 40951625, 2025). "Preliminary assessments indicated hypoglycemia (capillary blood glucose 35-40 mg/dL) without any prior history of diabetes, insulin, or sulfonylurea administration." (PMID 41333493, 2025). "T1D, which only accounts for 5–10% of all diabetes cases, is a chronic disease characterized by a complete absence of insulin secretion." (PMID 40559766, 2025). "The gestational age of PGDM patients was smaller than that of GDM patients, while the proportion of family history of diabetes, FBG, 2hPBG, HbA1c and the proportion of insulin used were significantly higher than those of GDM patients, with statistical significance (P<0.05)." (PMID 40607223, 2025). "Diabetes mellitus (DM) is an incurable chronic disease characterized by a metabolic syndrome resulting from a lack of insulin and/or its inability to exert its effects." (PMID 40545698, 2025). "She had hepatomegaly without clinically significant fibrosis, and slightly elevated fasting insulin without diabetes." (PMID 40842493, 2025).
diabetes (continued). "Participants felt that staff looking after them often did not have enough knowledge about diabetes and insulin management." (PMID 41358572, 2025). "In parallel, the evolution of the insulin pump came to enhance the effect of CGM on metabolic control, with the hybrid closed loop (HCL) being the most promising entry in diabetes technology, implementing the communication of CGM with the insulin pump in clinical practice." (PMID 41462808, 2025). "Diabetes mellitus (DM) is an intricate metabolic disorder marked by persistent hyperglycemia, arising from disruptions in glucose metabolism, with two main forms, type 1 and type 2, involving distinct etiologies affecting β-cell destruction or insulin levels and sensitivity." (PMID 39136514, 2025). "For the top 5% of high income earners, decreased risk of severe hypoglycemia with higher income was consistently observed across all subgroups, irrespective of gender, diabetes duration, insulin use, or CKD status." (PMID 40455444, 2025). "Triglyceride glucose-body mass index has superiority in assessing IR in both patients with and without diabetes and applicability to all subjects regardless of their status as recipients of insulin treatment." (PMID 40177184, 2025). "While insulin is the primary focus in diabetes treatment, the significance of glucagon should not be overlooked." (PMID 39996055, 2025). "We report a unique patient with no prior history of diabetes or autoimmune disease whose treatment with CPI for metastatic melanoma was complicated by CPI-D requiring insulin therapy." (PMID 40813111, 2025). "In the treatment of diabetes, 16.8% of participants used insulin, 67.4% took oral hypoglycemic drugs, and 15.9% did not receive treatment." (PMID 40408408, 2025). "Insulin levels and homeostatic model assessment for insulin resistance were high; however, no diabetes was detected." (PMID 40842493, 2025). "In the diabetes network, the unconditioned MASLD probability was 58%, with similar increases (~20%) observed after conditioning on high fasting insulin, BasalISR, or VAT, and low Clinsb, reinforcing the roles of hyperinsulinemia, insulin resistance, and visceral adiposity in hepatic steatosis." (PMID 40502600, 2025). "Accessibility of insulin pumps is also restricted in some countries and healthcare systems; thus, not all pregnant women with diabetes will be able to use them." (PMID 40125239, 2025). "Diabetes is defined as an increased glucose level in the blood due to a lack of insulin in our body and/or insulin resistance." (PMID 40019907, 2025). "It has been demonstrated that approximately 50% of insulin is secreted under basal conditions in healthy individuals without diabetes." (PMID 40114703, 2025). "Black and Asian pregnant women had higher HbA1c and serum glucose levels, as well as lower insulin production and higher insulin resistance, compared to White women, regardless of diabetes status." (PMID 39915864, 2025). "Type 2 diabetes mellitus (T2DM) is a prevalent chronic metabolic disease that affects over 400 million individuals globally and is characterized by insulin resistance, impaired insulin secretion, and hyperglycemia." (PMID 40863575, 2025). "Male mice with this predisposition (carrying a MIDY-like INS gene mutation, R (B22)E) exhibit glucose intolerance and rapidly develop frank diabetes upon HFD exposure, but do not develop diabetes when on a regular diet." (PMID 40109403, 2025). "While a recent patient‐reported experience measure for adult diabetes inpatient care has been developed and validated, this does not focus on insulin management specifically." (PMID 41358572, 2025). "DM is categorized into two major classes: Type-1 DM (insulin-reliant diabetes mellitus) and Type-2 DM (non-insulin reliant diabetes mellitus)." (PMID 41011204, 2025). "Insulin-treated older adults (≥66 years) with ADRD and diabetes were included." (PMID 41329488, 2025).